IFNG (interferon gamma)
Diseases named in the same sentence as IFNG in open-access papers (continued):
Sharing a sentence is not in itself a finding about the gene and the disease.
Autoimmunity (continued). "Moreover, these cells did not secrete either IFNγ or IL-2 cytokines following T cell stimulation, suggesting their ability to suppress autoimmunity." (PMID 23243423, 2012). "In psoriatic lesions, cytokines like IL-6, IL-12p70, IFNγ and TNFα are identified, together with chemokines like CCL2-5 and CXCL1, which shows that several of the cocktails stimulate cytokines and chemokines that to a large extent overlap with the ones expressed in different autoimmune conditions." (PMID 20663192, 2010). "Therefore, our data may provide some explanation as to how perturbations to PTPN22 promote autoimmunity later in life, following an alteration of ICAM-1-LFA-1 responsiveness over time, which accumulates to promote the expansion of inflammatory IFNγ responses with aging." (PMID 30054208, 2018). "Dual IFNγ and IL-17 producing CD4+ Th cells called Th17.1, non-classic Th1, and ex-Th17 cells are identified in various autoimmune conditions, often at sites of inflammation." (PMID 35860254, 2022). "Only one patient within the non-relapsed cohort developed secondary autoimmunity (microscopic colitis) at 2 months post-AHSCT and this was reflected in a brief elevation in the concentration of cytokines at 3 months, such as IFNγ and IL-10." (PMID 35126353, 2021).
Obesity (328 papers, 2010 to 2026). Accumulation of substantial excess body fat. "The pathway of elevated CCL2 gene expression associated with obesity specifically involves Interferon-gamma (IFN-γ) pretreatment." (PMID 39334887, 2024). "In the low-grade systemic inflammation associated with obesity, interferon-gamma (IFN-γ) secreted by CD4+ and CD8+ lymphocytes can activate STAT1 in adipocytes, leading to dysfunctional adipocyte function and insulin resistance." (PMID 39564133, 2024). "We and others have previously reported that IFNγ levels are elevated in individuals with obesity and obese animals, and reduced IFNγ levels are associated with improved insulin action and glucose metabolism." (PMID 38951527, 2024). "Alleviation of hypothalamic inflammation and deficiency in interferon gamma (IFN-γ) also reduced food intake and diet-induced obesity." (PMID 35911732, 2022). "Our comprehensive investigation highlights a central role for IFNγ in mediating obesity-associated inflammation in humans." (PMID 36153324, 2022). "The underlying chronic Th1 inflammation in individuals with obesity leads to an increase of pro-inflammatory cytokines, such as IFNγ, while anti-inflammatory cytokines, such as IL-10 are decreased." (PMID 35844529, 2022). "As diet-induced obesity is associated with increasing numbers of intestinal IFNγ-expressing T cells, this IFNγ-Irgm1 axis probably constitutes another important means by which immune cells alter bacterial taxa to promote metabolic disease." (PMID 33972511, 2021). "By contrast, obesity-associated adipose tissue expansion is accompanied by an increase in elastase-secreting neutrophils, mast cells, and IFNγ-secreting CD8+ T cells, Th1 cells, and natural killer (NK) cells." (PMID 29799467, 2018). "Early during infection (i.e., d3 p.i.), obesity was again associated with reduced production of cytokines IL-13, IL-5, IL-12p70, IFNγ, TNFα, IL6, and IL-1β, as well as IL-28b (IFNλ), IL-17, and IL-15." (PMID 26110868, 2015). "However, combinations of obesity and ERα deficiency induced IFNγ production to deplete ST2+ oVAT Tregs, exacerbating oVAT inflammation and insulin resistance." (PMID 41764729, 2026). "Furthermore, KRAS mutations combined with lifestyle factors, such as obesity, exacerbate NK cell suppression by increasing interleukin-6 (IL-6) production and decreasing interferon-gamma (IFN-γ) levels, impairing NK cell-mediated immune responses." (PMID 39859231, 2025). "In general, obesity is associated with elevated levels of cytokines originating from both Th2 and Th1 immune responses, including interleukin (IL)-5, IL-10, IL-12, IL-13, Interferon-gamma (IFN-γ), and tumor necrosis factor alpha (TNF-α)." (PMID 41007770, 2025). "A study has also confirmed that Treg numbers are reduced in obese human ATs and that increased IFNγ production may play an important role in AT Treg loss and obesity‐associated inflammation in humans." (PMID 38812572, 2024). "Here, we used mice with conditional loss of IFNγ signaling in myeloid cells to explore the hypothesis that macrophage IFNγ signaling regulates obesity-mediated insulin resistance in the liver and MASH." (PMID 38951527, 2024). "Taken together, the signaling interaction between leptin and IFNγ, particularly in adipose tissue of obese individuals, may play a key modulating role in obesity-associated metabolic disorders and development of pathology." (PMID 33379198, 2020). "We observed that increased concentrations of TNFα and IFNγ, associated with obesity and diabetes, might interfere with the anti-inflammatory effect of insulin, which in turn might promote inflammation." (PMID 31504048, 2019). "Moreover, Tregs associated with obesity and hyperinsulinemia are deregulated with reduced IL-10 production and increased interferon gamma (IFN-γ) production, exacerbating meta-inflammation." (PMID 31475003, 2019).
Obesity (continued). "To verify that expression of the genes analyzed in general was not static but could be modified by other stimuli, we subjected the cells to other obesity-associated stimuli (TNFα, IFNγ) or inflammatory stimuli (Pam3Cys, LPS) and observed various changes in gene expression." (PMID 32849273, 2020). "Notably, the top upregulated transcriptional regulators in the liver of both HFD and ARE-Del-/- mice displayed an overlap, suggesting that IFNγ may be a primary cytokine in obesity-associated inflammatory responses." (PMID 33379198, 2020). "Therefore, the upregulation of melatonin observed in the placebo might be due to the endogenous melatonin synthesis to counteract obesity-associated inflammation as evidenced by the strong correlation between Δ melatonin and Δ IFNγ found only in the placebo group (r = 0.54, p = 0.02)." (PMID 40077655, 2025). "Both IFNγ and IL-8 are upregulated in obesity compared with those at normal weight and downregulated at 6 and 12 months following surgical weight loss." (PMID 40145019, 2025). "Our data suggest that obesity-associated CD8+ TIL dysfunction and decreased production of IFNγ limits tumor MHC-I expression." (PMID 38565540, 2024). "Levels of IL-1RA and IFNγ were elevated with pregravid obesity, whereas GM-CSF and EGF concentrations were decreased." (PMID 39872537, 2024). "In 4 h unstimulated cells, IFNγ was the gene with the most significantly lower expression in adolescents with obesity compared to controls." (PMID 38741712, 2024). "CD8+ T cells, recognized as cytotoxic T lymphocytes, proliferate in quantity during obesity and exhibit an elevated capability to release cytokines (IFNγ) and cytotoxic substances (perforin and granzymes) while engaging in direct cell‐to‐cell contact." (PMID 38812572, 2024). "High levels of adipokines, inflammatory modulators in obesity, are responsible for the secretion of pro-inflammatory cytokines, such as IFNγ, TNFα, IL-1β, IL-6, and IL-12." (PMID 39519568, 2024). "In the ANS/inflammation-induced obesity network, the fibrilin 1 (FBN1) gene, encoding the asprosin hormone, interacts only with IL6, which, in turn, interacts with interferon gamma (IFNG)." (PMID 39062927, 2024). "More interestingly, FBN1 interacts directly with IFNG in stress-induced obesity but with IL6 in ANS/inflammation-induced obesity." (PMID 39062927, 2024). "PD-1 expression in these macrophages is induced by obesity-related factors, including IFNγ, TNF, leptin, insulin and palmitate." (PMID 39402302, 2024). "Interferon-γ (IFNγ) is a pro-inflammatory cytokine elevated in obesity and modulating macrophage functions." (PMID 38951527, 2024). "Due to adipose tissue dysfunction in states of obesity, WAT predominantly expresses proinflammatory adipokines and cytokines, such as Il-1b, Il-6, Il-12, TNF-α or interferon gamma, which contribute to the conditions of chronic systemic inflammation in obesity." (PMID 37239098, 2023). "IFNγ and MCP-1 are pro-inflammatory cytokines that play an important role in obesity-induced inflammatory responses and are linked to an increased risk for CVD and type 2 diabetes." (PMID 36771387, 2023). "Taken together, these data indicate that adipocyte metabolic function becomes impaired with progressive obesity, while adaptive immune capability increases, underscoring the likely dual effects of IFNγ." (PMID 36153324, 2022). "Especially in individuals with obesity, leptin leads to an increased secretion on IFNγ and suppression of Th2." (PMID 35844529, 2022). "Here the authors propose a role for interferon gamma in shrinking the adipose tissue regulatory T cell compartment seen in human obesity and assess the alterations seen during induction of dietary changes." (PMID 36153324, 2022). "HFD-induced obesity leads to elevated levels of many inflammatory cytokines in eVAT, notably TNFα, IFNγ, and IFNα." (PMID 36337732, 2022).
Obesity (continued). "In another study, obesity was associated with a decreased number of activated CD8+ T cells expressing CD28, CD40 ligand (CD40L), IFNγ as well as both IFNγ and GrB, and both CD28 and interleukin 12 receptor (IL12R)." (PMID 36295052, 2022). "For instance, children with obesity also have dysregulated NK cells but in contrast to our cohort, they have reduced cytotoxicity, normal IFNγ production, normal mitochondrial mass and increased basal ECAR." (PMID 36276144, 2022). "In obesity, there is evidence that interferon gamma-producing pro-inflammatory CD4‐positive Th1 cells are increased, whereas anti‐inflammatory CD4‐positive Th2 and Treg cells are reduced." (PMID 36376974, 2022). "With obesity, there is altered levels of catecholamines, glucose, and cytokines such as IFNγ, but also hormones like leptin and insulin." (PMID 36713396, 2022). "In human obesity, these global effects of interferon gamma to reduce regulatory T cells and diminish their function appear to instigate adipose inflammation and suppress adipocyte metabolism, leading to insulin resistance." (PMID 36153324, 2022). "CD64 expression was significantly reduced on monocyte-derived macrophages from mothers with obesity both after 7 days of differentiation (10-fold lower) as well as after IFNγ stimulation (2-fold lower) (left)." (PMID 34195568, 2021). "It should be noted that, the increased level of inflammatory cytokines were different in high-fat diet-induced obesity and genetic-induced obesity as IFNγ and TNF-α elevated in genetically-induced obesity, while IL-6 elevated in diet-induced obesity." (PMID 33827616, 2021). "Using the pathway explorative analysis tool of ingenuity pathway analysis (IPA) software, we identified two genes, TNFA and UBC (Ubiquitin C), that maximize the connection between obesity-related genes and IFNγ." (PMID 33379198, 2020). "CD8+ T cells, or cytotoxic T lymphocytes (CTLs), increase in the VAT during obesity and have an enhanced capacity to secrete IFNγ." (PMID 32499756, 2020). "IL1β, IL6, IL10, TNF, interferon gamma (IFNγ) and monocyte chemoattractant protein 1 (MCP1/CCL2), and obesity-associated maternal cytokines likely access the fetus via the placenta." (PMID 33158303, 2020). "To characterize the genetic interaction between IFNγ and obesity-related genes, we identified the 53 most significant variants (p ≤ 1 × 10−5), selected by the National Human Genome Research Institute GWAS catalog." (PMID 33379198, 2020). "TNFα signaling was one of top upstream transcriptional regulators in the liver of HFD mice, implying that IFNγ- and TNF-mediated inflammatory responses are major events in obesity-associated chronic inflammation." (PMID 33379198, 2020). "Using human GWAS data, we characterized the genetic interaction between significant obesity-related genes and IFNγ signaling and demonstrated that IFNγ is crucial for obesity-mediated inflammatory responses." (PMID 33379198, 2020). "As well, both obesity and aging are associated with a marked increase in the CD4/CD8 T cell ratio and higher T cell IFNγ production in response to anti-CD3 plus anti-CD28 stimulation." (PMID 32027700, 2020). "Several lines of evidence suggest that interferon-γ (IFNγ) and tumor necrosis factor-α (TNFα) levels are markedly increased in obesity." (PMID 31504048, 2019). "IDO-deficient mice displayed elevated liver fibrosis, increased hepatic macrophage infiltration, and higher concentrations of IL-1β, IL-6, and IFNγ in obesity." (PMID 31921154, 2019). "Mechanistically, macrophages activated with the elevation of lipopolysaccharide (LPS) and IFNγ in obesity acquire an inflammatory M1 phenotype, characterized by increased production of pro-inflammatory cytokines and reactive oxygen species (ROS)." (PMID 29374208, 2018). "IFNγ-knockout in obesity improved insulin sensitivity and decreased adipocyte size, macrophage infiltration and cytokine expression." (PMID 29254175, 2017).
Obesity (continued). "They produce pro-inflammatory cytokines, notably tumor necrosis factor alpha (TNFα) and interferon gamma (IFNγ), and regulate macrophages to promote insulin resistance in obesity." (PMID 29163547, 2017). "Mast cells were supposed to promote diet-induced obesity and glucose intolerance by the production of IL-6 and IFNγ." (PMID 23964268, 2013). "Macrophages accumulate in adipose tissue during obesity and IFNγ produced by these macrophages was recently shown to regulate fat inflammation during obesity." (PMID 20877574, 2010). "A high-fat diet and obesity are associated with chronic low-grade systemic inflammation and can induce the secretion of proinflammatory cytokines, such as tumor necrosis factor alpha (TNF-α, interleukin-1 (IL-1), and interferon gamma (IFN-γ)." (PMID 35887932, 2022). "After stimulation by lipopolysaccharide (LPS) and interferon gamma (IFN-γ), macrophages develop the classic state of pro-inflammatory activation (M1), which generates bactericidal or Th1 responses, which are typically associated with obesity." (PMID 36648872, 2022). "Moreover, the footprint of excess IFNγ is suggested by increased adipocyte STAT1 expression in obesity and following short-term HFD administration in lean subjects." (PMID 36153324, 2022). "During obesity, Th1 cells increase within the adipose tissue, which could have an inhibitory effect on Th2 cells through the production of IFNγ." (PMID 35844529, 2022). "IFNG is one of the most important cytokines mediating systemic inflammation in obesity." (PMID 36235679, 2022). "Finally, our studies indicate a role for IFNγ in human Treg apoptosis and death in obesity through a process resembling exhaustion." (PMID 36153324, 2022). "The expression of proinflammatory markers, that are in the basis of obesity induced inflammation, such as TNFα, IL-6, IL-12, interferon gamma (IFNγ) and monocyte chemotactic protein-1 (MCP-1) were controlled with valsartan as well as adequate levels of adiponectin in adipocytes." (PMID 36419097, 2022). "It has been shown that in obesity, there is a decrease in the proliferative capacity of T cells, production of interferon gamma (IFNγ) and TNF-α, and increased expression of PD-1, which may be associated with leptin signaling." (PMID 35164764, 2022). "This decline appears to be a key contributor to obesity-induced insulin resistance as suggested by our observations herein demonstrating that human adipocytes can present antigen to activate IFNγ-producing Th1 cells and that ingestion of HFD induces a rapid drop in AT Tregs." (PMID 36153324, 2022). "Moreover, in high-fat diet mice and PBC murine models, IFNγ signaling is crucial for obesity-mediated inflammatory responses." (PMID 36605198, 2022). "This suggests that IFNγ may suppress VAT Treg function in obesity by promoting PD-1 expression and an exhausted phenotype." (PMID 36337732, 2022). "Therefore, we next investigated the impact of pregravid obesity on macrophage polarization potential using in vitro differentiation of monocytes collected at T3 using IFNγ (M1 like) and IL-4 (M2 like) conditioning." (PMID 34195568, 2021). "Notably, regardless of phenotype, total effector and naive CD8 TIL subsets and intratumoral IFNγ concentration were decreased with obesity." (PMID 33123173, 2020). "Therefore, obesity-induced IFNγ signaling can be aggravated by infectious, genetic and environmental factors to break this immune tolerance barrier in the host immune system." (PMID 33379198, 2020). "In addition, no inhibitory effect was observed after stimulation with cytokines TNFα and IFNγ, which are both elevated in obesity." (PMID 32849273, 2020). "While increased IFNγ secretion by NK cells drives metabolic dysfunction during early-stage obesity, TNFα secretion by NK cells may play a larger role in driving inflammation and metabolic dysfunction during chronic obesity." (PMID 32499756, 2020).